JRKL (JRK like)
Synonyms: HHMJG
Tractability: PROTAC: ubiquitination databases record sites on it.
Gene: Protein-coding gene on chromosome 11 (96,389,989 to 96,507,574, forward strand). Ensembl gene ENSG00000183340.
Subcellular location: Nucleus
Subcellular location (Human Protein Atlas): Nucleoplasm; Cytokinetic bridge
Gene Ontology:
Molecular function: DNA binding; nucleic acid binding
Biological process: central nervous system development
Cellular component: nucleus
Genetic constraint (gnomAD): Loss-of-function variants: 27 observed, 37.17 expected, observed/expected ratio (o/e) 0.73, 90% interval 0.53 to 1. The upper end of that interval is the gene's LOEUF score, 1, which puts it in group 4 of 6, group 1 being the genes least tolerant of losing a copy. Missense variants: 495 observed, 647.12 expected, observed/expected ratio (o/e) 0.76, 90% interval 0.71 to 0.82. Synonymous variants: 204 observed, 225.36 expected, observed/expected ratio (o/e) 0.91, 90% interval 0.81 to 1.02.
Homologues: Orthologues: chimpanzee JRKL (99% identical), macaque JRKL (99% identical), dog JRKL (96% identical), pig JRKL (96% identical), rabbit JRKL (95% identical), mouse Jrkl (94% identical), rat Jrkl (93% identical). Paralogues in human: TIGD2 (62% identical), JRK (35% identical), TIGD7 (30% identical), TIGD1 (27% identical), TIGD5 (27% identical), TIGD4 (23% identical), TIGD6 (23% identical), CENPB (21% identical), TIGD3 (18% identical), POGZ (17% identical), POGK (16% identical).
Diseases named in the same sentence as JRKL in open-access papers:
JRKL is named in the same sentence as 4 diseases in open-access papers, as found by Europe PMC text mining. Sharing a sentence is not in itself a finding about the gene and the disease. The quoted sentences say what the papers report.
breast carcinoma (1 paper, 2022). "Here we speculated that the gain or loss of enhancer-promoter interactions and their corresponding DEGs such as up-regulated JRKL and down-regulate FA2H may constitute potential diagnostic or therapeutic targets for reversing doxorubicin resistance in breast cancer." (PMID 36003143, 2022).
epilepsy (1 paper, 2012). A brain disorder characterized by episodes of abnormally increased neuronal discharge resulting in transient episodes of sensory or motor neurological dysfunction, or psychic dysfunction. "Although TIGD7 and JRKL are both homologs of the Jrk “jerky” gene associated with epilepsy in mice, they do not have known relevance in cancer development." (PMID 22759657, 2012).
JRKL also shares sentences with these, for which no sentence is quoted: cancer (2 papers); psoriasis (1).